TMEM65 (transmembrane protein 65)
Description:
Mitochondrial protein that plays a critical role in the sodium-dependent calcium efflux from mitochondrion. The precise role of TMEM65 in mitochondrial sodium/calcium exchange is however unclear: TMEM65 associates with the SLC8B1/NCLX antiporter and probably promotes the sodium/calcium exchange mediated by SLC8B1/NCLX. According to another report, TMEM65 functions as the mitochondrial sodium/calcium antiporter itself: homodimerization drives formation of a pocket capable of binding calcium. Essential for maintaining proper cardiac intercalated disk (ICD) structure and function as well as cardiac conduction velocity in the heart (By similarity). Its association with SCN1B is required for stabilizing the perinexus in the ICD and for localization of GJA1 and SCN5A to the ICD (By similarity).
Tractability: Antibody: UniProt places it where antibodies can reach, with high confidence; its Gene Ontology location is reachable by antibodies, with high confidence; UniProt predicts a signal peptide or a membrane-spanning region; the Human Protein Atlas places it where antibodies can reach. PROTAC: its protein half-life has been measured.
Gene: Protein-coding gene on chromosome 8 (124,306,189 to 124,372,701, reverse strand). Ensembl gene ENSG00000164983.
Subcellular location: Mitochondrion inner membrane; Cell membrane
Subcellular location (Human Protein Atlas): Plasma membrane; Vesicles
Gene Ontology:
Molecular function: calcium:sodium antiporter activity; protein binding
Biological process: calcium export from the mitochondrion; cardiac conduction; cardiac ventricle development; regulation of cardiac conduction; sodium ion transmembrane transport
Cellular component: intercalated disc; mitochondrial inner membrane; mitochondrion; plasma membrane
Genetic constraint (gnomAD): Loss-of-function variants: 10 observed, 7.81 expected, observed/expected ratio (o/e) 1.28, 90% interval 0.78 to 1.88. That is too few expected variants to judge how well the gene tolerates losing a copy. Missense variants: 148 observed, 131.18 expected, observed/expected ratio (o/e) 1.13, 90% interval 0.99 to 1.29. Synonymous variants: 80 observed, 50.58 expected, observed/expected ratio (o/e) 1.58, 90% interval 1.32 to 1.88.
Gene-disease validity (ClinGen):
ClinGen rates the evidence that TMEM65 causes each of these diseases.
mitochondrial disease (autosomal recessive): Limited.
Homologues: Orthologues: chimpanzee TMEM65 (99% identical), macaque TMEM65 (98% identical), pig TMEM65 (93% identical), mouse Tmem65 (91% identical), rat Tmem65 (90% identical), guinea pig TMEM65 (70% identical), tropical clawed frog tmem65 (67% identical), zebrafish tmem65 (52% identical), Caenorhabditis elegans tag-321 (36% identical), Drosophila melanogaster CG17715 (35% identical), Caenorhabditis elegans C03B8.3 (22% identical).
Diseases named in the same sentence as TMEM65 in open-access papers:
TMEM65 is named in the same sentence as 22 diseases in open-access papers, as found by Europe PMC text mining. Sharing a sentence is not in itself a finding about the gene and the disease. The quoted sentences say what the papers report.
breast carcinoma (2 papers, 2023 to 2025). "However, the biological function, mechanism of action, and regulatory mechanism of TMEM65 in breast cancer including TNBC remain unexplored." (PMID 40546127, 2025).
cardiomyopathy (2 papers, 2022 to 2025). A disease of the heart muscle or myocardium proper. "Since cardiomyopathy is often associated with changes in action potential (AP) profiles as a result of ion channel remodeling, we compared QT intervals and APs between Tmem65 KD and control hearts." (PMID 36257954, 2022). "Here the authors report that knockdown of the ICD-bound transmembrane protein 65 results in impaired ICD structure, abnormal cardiac electrophysiology and cardiomyopathy in mice." (PMID 36257954, 2022). "We conclude that disrupting Tmem65 function results in impaired ICD structure, abnormal cardiac electrophysiology, and ultimately cardiomyopathy." (PMID 36257954, 2022).
developmental delay (2 papers, 2020 to 2025). "The sole patient reported with biallelic TMEM65 variants displayed microcephaly, seizures, vision loss, and global developmental delay." (PMID 33426505, 2020).
mitochondrial encephalomyopathy (2 papers, 2025 to 2026). A heterogenous group of disorders characterized by alterations of mitochondrial metabolism that result in muscle and nervous system dysfunction. "Transmembrane protein 65 (TMEM65) depletion in a patient caused severe mitochondrial encephalomyopathy, highlighting its clinical importance." (PMID 41980949, 2026).
Arrhythmia (1 paper, 2022). Any cardiac rhythm other than the normal sinus rhythm. "One alternative for overcoming this limitation and for confirming a causative relationship to arrhythmia would be to establish ambulatory ECG in adult mice following disrupting Tmem65 expression." (PMID 36257954, 2022). "Although the presence of arrhythmia remains to be determined, our study has demonstrated, with multiple lines of evidence, that Tmem65 KD is associated with the arrhythmogenic nature in the heart." (PMID 36257954, 2022). "One limitation to this study is the inability to capture arrhythmia on ECG in Tmem65 KD mice and is primarily due to several technical challenges." (PMID 36257954, 2022).
congestive heart failure (1 paper, 2022). Failure of the heart to pump a sufficient amount of blood to meet the needs of the body tissues, resulting in tissue congestion and edema. "Tmem65 KD mouse hearts ultimately developed dilated cardiomyopathy, severe fibrosis, and congestive heart failure." (PMID 36257954, 2022). "This reduction in Tmem65 leads to clear signs of congestive heart failure (CHF)—including dilated ventricle with fibrosis, reduced cardiac output, increased expression in protein stress markers - by 6–7 weeks post injection, with all mice expiring 7 weeks post injection." (PMID 36257954, 2022). "All the male Tmem65 KD mice died after 60 days post injection, while most female mice (11 of 13 total, 85%) survived until weeks 6–7 even though they also showed similar signs of illness as described for males, with evidence of congestive heart failure (CHF)." (PMID 36257954, 2022).
dilated cardiomyopathy (1 paper, 2022). Cardiomyopathy which is characterized by dilation and contractile dysfunction of the left and right ventricles. "Collectively, the results above demonstrate clear evidence of dilated cardiomyopathy by 6–7 weeks after intraperitoneal injection of Tmem65 shRNA." (PMID 36257954, 2022). "Tmem65 knockdown (KD) results in increased mortality which is accompanied by eccentric hypertrophic cardiomyopathy within 3 weeks of injection and progression to dilated cardiomyopathy with severe cardiac fibrosis by 7 weeks post-injection." (PMID 36257954, 2022). "In addition, the anterior and posterior wall thickness of the left ventricle in Tmem65 KD mice decreased (P < 0.01) when compared to those of controls, implying dilated cardiomyopathy." (PMID 36257954, 2022).
hypertrophic cardiomyopathy (1 paper, 2022). A condition in which the myocardium is hypertrophied without an obvious cause. "Moreover, ventricular cross sections showed dilated lumens of both ventricles in Tmem65 KD hearts than control hearts, while the ventricular wall thickness in both groups was comparable, suggesting eccentric hypertrophic cardiomyopathy." (PMID 36257954, 2022).
lung carcinoma (1 paper, 2017). "For example, the mitochondrial protein TMEM65 is amplified and overexpressed in ~50% of BM from breast and lung cancers, SOX11 is amplified and overexpressed in ~30% of breast and ~80% of lung cancer-BM, and NRG1 is lost and suppressed in ~60% of BCBM." (PMID 28098771, 2017).
Mitochondrial myopathy (1 paper, 2020). "Transmembrane protein 65 (TMEM65) is a mitochondrial inner-membrane protein; dysfunction of TMEM65 results in mitochondrial myopathy." (PMID 33322792, 2020).
cancer (6 papers, 2022 to 2025). A tumor composed of atypical neoplastic, often pleomorphic cells that invade other tissues. "Here, it is first reported that human transmembrane protein 65 (TMEM65), a poorly characterized mitochondrial inner‐membrane protein‐encoding gene in human cancer, acts as a novel oncogene in TNBC to promote tumor growth, metastasis, and cisplatin resistance both in vivo and in vitro." (PMID 40546127, 2025). "Other researchers have carried out Transmembrane protein 65 (TMEM65) pan‐cancer studies, and the results found TMEM65 to be associated with certain pathways (TGF beta signalling, TNFA signalling, hypoxia, pyroptosis, DNA repairing, autophagy, ferroptosis, ferroptosis and ferroptosis) in BC." (PMID 37849388, 2023). "Our data shed light on CHD6 upstream regulatory circuit and reveal how EGF/Wnt oncogenic signal promotes CHD6’s downstream activity toward TMEM65 pathway to cause deregulation of mitochondrial dynamics and subsequently promote cancer metastasis and tumorigenesis." (PMID 36473865, 2022). "Third, TMEM65 acts as a novel regulator of TNBC stemness by activating the OXPHOS‐ROS‐HIF1α‐SERPINB3 pathway to promote cancer progression and chemoresistance." (PMID 40546127, 2025). "First, TMEM65 acts as a novel oncogene in TNBC to promote cancer progression and cisplatin resistance." (PMID 40546127, 2025). "Our understanding of the biological role of CHD6 in regulating TMEM65-mediated mitochondrial dynamics and metastasis of cancer reveals therapeutic strategies for cancer intervention and treatment." (PMID 36473865, 2022). "We additionally illustrated that the regulation network of EGF-AKT signaling in stabilizing CHD6, and consequent accumulation of TMEM65 during cancer formation can be blocked by Cetuximab treatment." (PMID 36473865, 2022). "Noticeably, TMEM65 is overexpressed in cancer, which is consistent with the role of its upstream regulator CHD6 as CHD6 is also highly expressed in CRC." (PMID 36473865, 2022). "CHD6 collaborates with TCF4 to positively regulate TMEM65 gene expression, thereby impacting mitochondrial homeostasis and promoting cancer growth and metastasis." (PMID 36473865, 2022). "As it has been documented that SERPINB3 regulates cancer stemness, we next examined whether TMEM65 affects TNBC stemness via SERPINB3." (PMID 40546127, 2025). "As cancer stemness is intimately linked to chemoresistance in TNBC and cisplatin is a commonly used chemotherapy drug for TNBC patients, we next examined the effects of TMEM65 on the sensitivity of TNBC cells to cisplatin." (PMID 40546127, 2025). "As a novel regulator of cancer stemness, whether elevated expression of TMEM65 contributes to therapeutic resistance to other chemotherapy agents (in addition to cisplatin) or targeted therapeutic drugs remains to be explored in future studies." (PMID 40546127, 2025). "Moreover, we identify CHD6 downstream target TMEM65, which is a mitochondrial protein overexpressed in many cancers and is involved in regulating mitochondrial dynamics." (PMID 36473865, 2022). "Together, the correlation between CHD6 and TMEM65 could be recapitulated in mouse xenograft cancer model, and deregulation of TMEM65 level may play roles in CHD6-mediated tumorigenicity." (PMID 36473865, 2022).
tumor (6 papers, 2018 to 2025). "In vivo, xenograft tumor experiments also demonstrated that re‐expression of SERPINB3 partially restored the reduced xenograft tumor growth caused by knockdown of TMEM65." (PMID 40546127, 2025). "The results showed that knockdown of MYC or TET3 alone significantly attenuated TMEM65‐induced xenograft tumor growth, and the more pronounced inhibitory effects were observed following simultaneous knockdown of MYC and TET3." (PMID 40546127, 2025). "To verify the effect of TMEM65 on cell migration in vivo, we further assessed the effect of TMEM65 on tumor metastasis using shTMEM65 to establish stably knockdown TMEM65 in MKN74 cell lines." (PMID 38341472, 2024). "To gain insight into the molecular mechanistic basis of the tumor promoting effect of TMEM65 in GC, we sought to identify its interacting partners by Co-IP followed by identification of the associated proteins using LC-MS." (PMID 38341472, 2024). "The results showed that TMEM65 knockdown significantly reduced tumor volume (P < 0.001) and tumor weight (P < 0.05)." (PMID 38341472, 2024). "After stratification by tumor staging, high TMEM65 predicted poor prognosis in stage III-IV GC patients (P < 0.05) but not in stage I-II patients." (PMID 38341472, 2024). "Conversely, silencing of TMEM65 in GC cells showed opposite abilities on cell function in vitro and suppressed tumor growth and lung metastasis in vivo (all P < 0.01)." (PMID 38341472, 2024). "Importantly, the depletion of TMEM65 significantly reduced tumor volume and weight in mouse xenograft tumor models." (PMID 40546127, 2025). "In line with the oncogenic function of TMEM65, targeting depletion of TMEM65 by VNP-encapsulated TMEM65-siRNA significantly suppressed tumor growth in subcutaneous xenograft tumor model, and TMEM65 could serve as a therapeutic target in GC." (PMID 38341472, 2024). "We injected VNP-siTMEM65 or VNP-siNC into the xenograft tumor in the experimental group and the control group, the results showed that targeting depletion of TMEM65 by VNP-siTMEM65 in GC cells significantly reduced tumor volume (P < 0.001) and tumor weight (P < 0.01)." (PMID 38341472, 2024). "We further verified the tumor-promoting properties of TMEM65 in vivo." (PMID 38341472, 2024). "Moreover, TMEM65 depletion by VNP-encapsulated TMEM65-siRNA significantly suppressed tumor growth in subcutaneous xenograft model." (PMID 38341472, 2024). "To avoid the potentially toxic effects of the combination administration of 10058‐F4 and Bobcat339 on mice, we stably knocked down MYC, TET3 alone or in combination in TMEM65‐overexpressing MDA‐231 cells and then carried out mouse xenograft tumor assays." (PMID 40546127, 2025). "This enhances the transcription of transmembrane protein 65 (TMEM65), a mitochondrial inner membrane protein, leading to sustained mitochondrial fusion, ATP overproduction, tumor growth, and metastasis." (PMID 38302953, 2024). "The data showed that CHD6 KD led to reduced liver metastasis, which can be reversed, at least in part, by TMEM65 overexpression in terms of number of metastasis and tumor area, suggesting a role of CHD6-TMEM65 axis in facilitating metastasis." (PMID 36473865, 2022). "In this study, we provide the first evidence that TMEM65 promotes TNBC cell proliferation, migration, and invasion in vitro and xenograft tumor growth and lung metastatic in vivo, and decreases TNBC cellular sensitivity to cisplatin in vitro and in mouse models." (PMID 40546127, 2025). "To examine whether TMEM65 promotes TNBC progression via regulating SERPINB3, we stably reintroduced SERPINB3 into TMEM65‐depleted SUM159PT and Hs578T cells, and then we carried out in vitro experiments and xenograft tumor growth assays in vivo." (PMID 40546127, 2025).
TMEM65 also shares sentences with these, for which no sentence is quoted: COVID-19 (2 papers); microcephaly (2); cardiac hypertrophy (1); colitis (1); colon tumor (1); colorectal cancer (1); fibrosis (1); heart failure (1); mitochondrial disease (1); respiratory failure (1).